MKI67 (marker of proliferation Ki-67)
Diseases named in the same sentence as MKI67 in open-access papers (continued):
Sharing a sentence is not in itself a finding about the gene and the disease.
COVID-19 (75 papers, 2020 to 2025). A disease caused by infection with severe acute respiratory syndrome coronavirus 2. "Interestingly, proliferative T cell subsets expressing MKi67 demonstrate distinct associations with COVID-19 severity and a general trend towards lymphopenia with an increase in symptom severity." (PMID 39712003, 2024). "This analysis revealed a pattern of gene expression in microglia from patients with COVID-19 that included a nearly complete downregulation of genes associated with cellular proliferation (MKI67, CENPF) and upregulation of the cell cycle arrest marker CDKN1A (encoding p21)." (PMID 38502186, 2024). "While antigen-specific T cells may confer protection against SARS-CoV-2 virus, lymphopenia is associated with severe COVID-19 and exhausted, senescent T cells and those expressing MKI67, a key proliferation marker, contribute to pathology." (PMID 36869729, 2023). "Expression of EZH2 and MKI67 in adults with COVID-19 (particularly severe) and children with dengue (particularly secondary) indicated the presence of proliferative, “pre-plasmablast” cells in the peripheral circulation of these groups." (PMID 37638019, 2023). "Performing RNAscope on COVID-19 post-mortem lung tissue from individuals who died of COVID-19, we confirmed that MKI67-expressing CD8+ T cells had lower levels of MALAT1 mRNA in situ." (PMID 36869729, 2023). "On the contrary, CDKN3 and MKI67 were clustered as another group with low expression in the normal sample and high expression in the COVID-19 sample." (PMID 37113134, 2023). "However, there is a trend towards an increase in proliferating NK cells (high MKi67) with an increase in COVID-19 severity." (PMID 39712003, 2024). "Among the overlapping cell types, we found that 49% of ADT-annotated activated effector T cells cluster (HLA-DR+CD38+, ADT cluster #15) are overlapped with GEX dividing T/NK cluster, indicating expression of both HLADRA/CD38 and MKI67 marks a unique T cell subset in COVID-19." (PMID 35064122, 2022). "We observed that MKI67-expressing TCR+ T cells within the GEX dividing T/NK cluster were increased in COVID-19 patients, which was further validated by using flow cytometry with the same samples and a different cohort, specifically in CD4+ T cells from progressive patients." (PMID 35064122, 2022). "Notably, previous studies identified an increase of the proliferating NK cells (high MKI67) with severity of COVID-19 and highlighted the role of IL-15 and TGF beta in the cell state generation, thus emphasising involvement of NK subtypes in COVID-19 pathogenesis." (PMID 36230912, 2022). "Then, five important IADEGs (AXL, MKI67, CDKN3, BCL2 and PTGS2) for severe COVID-19 were screened by random forest analysis." (PMID 37113134, 2023). "Focussing on the tissue, we used an independent patient cohort of post-mortem COVID-19 lung samples and demonstrated that MALAT1 suppression was indeed a marker of MKI67+ proliferating CD8+ T cells." (PMID 36869729, 2023). "Our single-cell analysis showed that, in patients with severe/critical COVID-19, CD8+ T cell clusters were found to have a proliferative phenotype with highly expressed MKI67 and PCNA." (PMID 37628961, 2023). "Increased levels of S100A8, MKI67, HSPA5, LYZ, CTSD, and IGHG1 were observed in COVID-19 patients." (PMID 39026676, 2024). "The second subset (Prelim_PB2) was proliferative, with MKI67 expression; however, within group Prelim_PB2, MKI67 was expressed only in adults with COVID-19 and children with dengue, but not in adults with dengue and children with COVID-19." (PMID 37638019, 2023). "Furthermore, AXL, MKI67, CDKN3, BCL2 and PTGS2 as a marker combination could be used as potential markers to identify severe COVID-19 patients." (PMID 37113134, 2023). "Therefore, AXL, MKI67, CDKN3, BCL2 and PTGS2 might be key markers for occurrence and development of severe COVID-19." (PMID 37113134, 2023).
colitis (73 papers, 2011 to 2026). Inflammation of the colon. "Previous work revealed that cold exposure alleviates colitis in mice; this study extends that finding by demonstrating that cold exposure enhances intestinal regeneration even in healthy mice, upregulating proliferation markers (Mki67, PCNA, Cyclin D1)." (PMID 41898256, 2026). "Interestingly, while I3C treated colitis mice (WT DSS + I3C) increased markers of goblet cells (Tff3 and Clca3b) and cellular proliferation (Mki67), this increased expression was not altered in the AhRΔIEC phenotype." (PMID 38397081, 2024).
osteosarcoma (66 papers, 2007 to 2026). A usually aggressive malignant bone-forming mesenchymal neoplasm, predominantly affecting adolescents and young adults. "MKI67, a prominent cancer marker, contributes to osteosarcoma progression by inducing cell proliferation." (PMID 40092698, 2025).
brain tumors (62 papers, 1992 to 2026). "To further investigate the relations between the cell decrease and proliferation ability, we looked at the association of the CKAP2L versus the commonly used proliferation biomarkers in the TCGA dataset, including MKI67 and MCM6 expression, which have been used in other brain tumor studies." (PMID 33375517, 2020). "To further support the proposal that the decrease of cell number was due to the decline of proliferation ability, we looked at the association of the CKAP2L versus two common proliferation biomarkers in the TCGA and CGGA datasets, including MKI67 and MCM6, often used in brain tumor studies." (PMID 33375517, 2020).
endometrial cancer (62 papers, 2007 to 2026). Primary or metastatic malignant neoplasm involving the endometrium (mucous membrane that lines the endometrial cavity). "Furthermore, we looked into the interaction of AM and 4-OH-TMX on the gene expression of CCND1 and MKI-67 in stromal endometrial cells, since several studies have proposed these genes as potential biomarkers for endometrial cancer development." (PMID 38004441, 2023). "Next, we analyzed the relationship between RCOR2 and the proliferation-related genes MKI67, CCND1, and PCNA under the mRNA levels, in endometrial cancer." (PMID 40936699, 2025). "Correlation analysis showed that all three genes, MKI67, CCND1, and PCNA, exhibited a significant positive correlation with RCOR2 mRNA expression in endometrial cancer tissues." (PMID 40936699, 2025). "Moreover, the qPCR results of proliferation-related genes, MKI67, CCND1, and PCNA, supported the regulatory effects of ROCR2 on endometrial cancer cell proliferation." (PMID 40936699, 2025). "Furthermore, WB showed that RCOR2 knockdown or overexpression could change the expression of MKI67, CCND1, and PCNA in endometrial cancer cells remarkedly, which further demonstrated at the protein level that RCOR2 the proliferation of endometrial cancer cells." (PMID 40936699, 2025).
diabetes (61 papers, 2012 to 2026). "We identified novel targets including CLTC (clathrin heavy chain), TNS2, PLCG1 and NIFK (nucleolar protein interacting with the FHA domain of MKI67) for specific therapy of diabetes mellitus and obesity." (PMID 36837510, 2023).
liver cancer (60 papers, 2010 to 2025). An epithelial or non-epithelial malignant neoplasm that arises from the liver. "The overexpression of MKI67 is linked to worse overall survival (OS) and increased reoccurrence rates in patients with HBV-related liver cancer." (PMID 40421085, 2025). "ZBTB7B bound to the promoters of known ZBTB7B targets genes, e.g., Irs1, as well as genes important in liver cancer, including Jun, Akt1, Ccnd1, and Mki67." (PMID 38225233, 2024). "Human Protein Atlas data further verified MKI67 upregulation in liver cancer through immunohistochemistry." (PMID 34724892, 2021). "Certain microRNAs in naive T cells are connected to MKI67 expression, suggesting that MKI67 may play a part in liver cancer related to both HBV and HCV." (PMID 40421085, 2025). "Cytotoxic CD8 T cells (CD8+GNLY+) were found to be a major source of cytokines and chemokines secretion in liver cancers with low clonality, while proliferative pre-exhaustion T cells (CD8+MKI67+CXCL13+) were the main source in liver cancers with high clonality." (PMID 36980203, 2023). "Furthermore, the gene–miRNA interaction network for MKI67 in liver cancer was also examined based on the miRWalk database." (PMID 34724892, 2021). "In contrast, proliferative pre-exhausted CD8+MKI67+CXCL13+) and regular pre-exhausted T cells (CD8+CXCL13+) were enriched in liver cancers with high clonality." (PMID 36980203, 2023). "Univariate and multivariate Cox regression analyses showed that the expression of CTSV, CXCL8, MKI67 and PRF1 were independent prognostic factors in liver cancer patients." (PMID 35902905, 2022). "Recent studies have also revealed a connection between MKI67 and HCV-related liver cancer." (PMID 40421085, 2025). "It was noted that memory CD4 T cells (CD4+CD69+) were enriched in liver cancers with low clonality, while proliferative pre-exhausted CD4 T cells (CD4+MKI67+CXCL13+) were enriched liver cancers with high clonality and a major source of cytokines and chemokines." (PMID 36980203, 2023).
invasive carcinoma (57 papers, 1988 to 2026). A carcinoma that is not confined to the epithelium, and has spread to the surrounding stroma. "In keeping with diagnostic anatomo-pathological experience, the relative expression of ERBB2, ESR1, PGR and MKI67 in our study was often higher in DCIS samples than in samples enriched for invasive carcinomas." (PMID 30342538, 2018).
sarcoma (52 papers, 2008 to 2025). A usually aggressive malignant neoplasm of the soft tissue or bone. "Furthermore, the level of MKI67 expression significantly differed in disease-free survival and overall survival with PADD (pancreatic adenocarcinoma), SARC (sarcoma), and UVM (uveal melanoma)." (PMID 34724892, 2021). "Additionally, we found that CNN3 mRNA expression had a significant positive correlation with the mRNA expression of two mesenchymal markers, Snail and vimentin (VIM), and two tumor proliferation markers, MKI67 and PCNA, in sarcoma." (PMID 32667904, 2020).
thyroid cancer (50 papers, 2005 to 2026). "In summary, this study suggests that PILRA, MKI67, and UBE2C may serve as both diagnostic biomarkers and therapeutic targets for breast and thyroid cancers." (PMID 41328437, 2025).
pituitary tumor (49 papers, 2012 to 2025). A benign or malignant neoplasm affecting the pituitary gland. "Ki-67 (encoded by the MKI67 gene), which is a marker of cell proliferation, plays an important role in the assessment of pituitary tumors." (PMID 40869149, 2025).
Obesity (48 papers, 2010 to 2025). Accumulation of substantial excess body fat. "The expression of the cell-proliferation marker MKI67 was also significantly increased in the endometrial polyps of postmenopausal females with obesity, suggesting that the BMI influences the proliferation marker." (PMID 39275286, 2024). "As observed in L-MEK-mice, the vagotomy procedure completely blocked obesity-induced upregulations of Foxm1, its target genes, and that of Mki67." (PMID 29208957, 2017). "In summary, in this study, six hub genes, including Mki67, Rac2, Itgb2, Emr1, Tyrobp and Csf1r were identified which could be used as therapeutic biomarkers for obesity." (PMID 36654490, 2023). "Mki67, one of the hub genes found in this study, is a marker of cell proliferation, and it has been found to have higher expression levels in SVF during obesity in response to adipose tissue expansion." (PMID 36654490, 2023). "Notably, hepatic ERK activation and marked increases in the expression levels of FoxM1 and its target genes as well as that of the Mki67 gene were observed as early as only 1 week after HFD loading when obesity had not yet become evident." (PMID 29208957, 2017).
prostate tumor (46 papers, 2008 to 2025). "Proliferation markers (MKI67 and PCNA) were highly expressed in prostate tumor tissue of Pten/Smad4 KO mice but barely detected in prostate tissue of Pten/Smad4/Kmt9α KO and Ctrl mice." (PMID 39885202, 2025).
Stroke (43 papers, 2010 to 2026). Sudden impairment of blood flow to a part of the brain due to occlusion or rupture of an artery to the brain. "Collectively, our findings identified MKI67+ microglia as the proliferative, CH25H+ as the neuroprotective, while OASL+ as the proinflammatory microglia subcluster which was associated with ischemic brain injury 3 days after stroke." (PMID 37183260, 2023). "The presence and location of this subcluster was verified using immunofluorescence labeling of MKI67, which revealed that MKI67+ subcluster resided in ischemic penumbra and the lateral ventricle, particularly in the subventricular zone (SVZ) 3 days after stroke." (PMID 37183260, 2023).
esophageal cancer (34 papers, 1999 to 2025). A primary or metastatic malignant neoplasm involving the esophagus. "In addition, correlation analysis of gene expression using TCGA data revealed a significant positive association between QSOX2 and the cell proliferation markers MKI67 and PCNA in the esophageal carcinoma (ESCA) cohort." (PMID 40433832, 2025).
viral infection (34 papers, 2010 to 2025). "We further found that heterogeneity within the SLAMF6+ subsets might exist, which include a population expressing high levels of MKI67 resembling Slamf6+Ki67+ cells displaying vigorous expansion in response to viral infection in pre-clinical models." (PMID 38287061, 2024). "Using multiplex RNA in situ hybridization spatially correlating viral infection to cell types of an organoid and scRNA‐Seq, we found that HAstV1 infects all detected cell types and induces expression of the cell proliferation marker MKI67." (PMID 34309190, 2021).
cervical intraepithelial neoplasia (33 papers, 2007 to 2026). "The positive expression of MKI67 in cervical conization tissues correlates with disease progression, highlighting its potential as a biomarker for monitoring the progression of cervical intraepithelial neoplasia (CIN)." (PMID 40508156, 2025).
soft tissue sarcoma (33 papers, 1999 to 2025). A malignant neoplasm arising from muscle tissue, adipose tissue, blood vessels, fibrous tissue, or other supportive tissues excluding the bones. "Currently, a high MKI67 expression predicts for poor prognosis in patients with retroperitoneal soft tissue sarcomas." (PMID 33061942, 2020).
mantle cell lymphoma (32 papers, 2005 to 2025). Mantle cell lymphoma is a rare form of malignant non-Hodgkin lymphoma affecting B lymphocytes in the lymph nodes in a region called the ``mantle zone''. "The fact that we found a correlation of some of the highlighted genes with the expression of MKI67, a marker of proliferation known to be critical in mantle cell lymphoma pathogenesis, suggests that the identified new markers are also potentially relevant." (PMID 35052318, 2022).
leukemia (30 papers, 2016 to 2025). A malignant (clonal) hematologic disorder, involving hematopoietic stem cells and characterized by the presence of primitive or atypical myeloid or lymphoid cells in the bone marrow and the blood. "The observed effects of the combination on KMT2A-r leukemia cell survival were associated with downregulated expression of genes involved in proliferation and cell cycle progression including MKI67, CCNB1, CENPV, CDK4 and cMYC in infant KMT2A-r leukemia cells PER-485, PER-703 and PER-494." (PMID 35677155, 2022). "However, according to particular datasets, MKI67 was expressed at low levels in CNS and brain cancers, BC, leukaemia, and kidney cancer." (PMID 34724892, 2021). "Compared with normal B cells, high expression of cell proliferation markers such as Mki67, Cdk6, Cdkn2a and Hist1h1b, was noted in this cluster, indicating a BBC2 leukemia cell identity." (PMID 38730491, 2024).
leiomyoma (29 papers, 2013 to 2026). A well-circumscribed benign smooth muscle neoplasm characterized by the presence of spindle cells with cigar-shaped nuclei, interlacing fascicles, and a whorled pattern.
lung NETs (28 papers, 2015 to 2026). "Because high MKI67 expression is associated with shorter survival in patients with pulmonary neuroendocrine tumors, including SCLC, a high expression of KIF11 in SCLC would be compatible with its high malignancy." (PMID 39000337, 2024).
myeloma (27 papers, 2008 to 2025). "This distinctive phenotype observed in MKI67+ plasma cells prompted us to investigate the potential relationship between cuproptosis and multiple myeloma (MM)." (PMID 40384935, 2025). "Additionally, the expression level of SRSF1 had a positive correlation with MKI67 expression in MM patients (r = 0.3567, and p < 0.0001), indicating the role of SRSF1 in myeloma development." (PMID 37206090, 2023). "Interestingly, this PHF19 high myeloma cell subtype also exhibited high expression of genes involved in cell cycle including HELLS, EZH2, TYMS, ZWINT, and MKI67." (PMID 34857028, 2021). "Interestingly, this PHF19high myeloma cell subpopulation seems to be the cell cycling fraction as they also exhibited high expression of genes involved in cell cycling including HELLS, EZH2, TYMS, ZWINT, and MKI67." (PMID 34857028, 2021).
neuroblastoma (27 papers, 2009 to 2025). Neuroblastoma (NB) is the most common solid, extracranial childhood tumor. "Neuroblastoma proliferation was not affected by either decrease in temperature or GFP-tagging and xenografts contained MKI67-positive human cells at 5 dpf." (PMID 31900415, 2020).
insulinoma (25 papers, 2013 to 2025). "A low expression of both TMEM219 mRNA and protein and a high mRNA expression of MKI67, were evident in the insulinoma samples, with circulating levels of the TMEM219 ligand IGFBP3 also being reduced, thus suggesting a dysregulation of the TMEM219 signaling." (PMID 38318298, 2024). "Interestingly, when testing miR-129-2 transfection in the insulinoma cell line, we confirmed a decrease in the expression of TMEM219, but more remarkably we detected an increase in MKI67 and Insulin mRNA levels." (PMID 38318298, 2024).
Adrenal Tumors (23 papers, 2011 to 2026). "Adrenocortical carcinoma samples were classified according to the European Network for the Study of Adrenal Tumors (ENSAT) scale from 2 to 4, and MKI67 proliferation index spanning between 2 and 50%." (PMID 30400009, 2019).
retinoblastoma (23 papers, 2013 to 2026). A malignant tumor that originates in the nuclear layer of the retina. "In most cases, well-known cell type markers were used to identify cell clusters, such as RXRG for cone precursors, MKI67 for retinoblastoma cells." (PMID 34815392, 2021). "The cells enriched in state-5 at the terminal of the branch shared a highly similar global expression profile with retinoblastoma cells that possess cell cycle (UBE2C, PTTG1, CCNB1) and proliferation (MKI67) properties." (PMID 34815392, 2021).
medulloblastoma (22 papers, 2009 to 2026). A malignant, invasive embryonal neoplasm arising from the cerebellum. "MKI67 results were obtained for 34 primary medulloblastomas and one recurrence." (PMID 19293793, 2009).
papilloma (20 papers, 2010 to 2024). A benign epithelial neoplasm that projects above the surrounding epithelial surface and consists of villous or arborescent outgrowths of fibrovascular stroma. "As determined by BrdU incorporation, mKi67 expression, and cytoplasmic beta-catenin expression, it appeared that BMDECs in papillomas and ulcers had features of malignancy as seen in tumor cells." (PMID 30546048, 2018). "Additionally, we analyzed the proliferation status of papillomas as well as of the IFE by MKI67‐immunolabeling." (PMID 33786987, 2021).